EPHB6 (EPH receptor B6)
Diseases named in the same sentence as EPHB6 in open-access papers (continued):
Sharing a sentence is not in itself a finding about the gene and the disease.
tumor (continued). "In further support of this, our analysis of the TCGA database revealed that EPHB6 expression negatively correlates with that of vimentin in TNBC tumours." (PMID 29700392, 2018). "This lack of effect on some TIC markers indicated that in the analysed cell lines, EPHB6 enhanced tumour initiation by expanding a restricted subset of TICs that expressed higher levels of OCT4 and accelerated tumour growth." (PMID 29700392, 2018). "In agreement, EPHB6 augments tumour initiation and expansion of TIC populations in animal models, ultimately confirming the role for this receptor in TIC biology." (PMID 29700392, 2018). "To assess EPHB6 effect on TNBC tumours, we injected MDA-pc3 or MDA-B6-M cells into mammary fat pads of NU(NCr)-Foxn1nu (athymic) and NOD.Cg-Prkdcscid Il2rgtm1Wjl/SzJ (NOD-SCID) mice (1.5 × 106 cells and 1.5 × 105 cells per animal, respectively)." (PMID 29700392, 2018). "This consistently resulted in more frequent development of EPHB6-positive tumours, and statistical analysis confirmed that EPHB6 supports expansion of TIC populations." (PMID 29700392, 2018). "EPHB6 activity in supporting cell proliferation suggests that it should be beneficial for some TNBC tumours to maintain its expression." (PMID 29700392, 2018). "In agreement, patients with higher EPHB6 expression in their tumours have a better chance for recurrence-free survival." (PMID 29700392, 2018). "As a control, EPHB6 overexpression/downregulation was confirmed by immunohistochemistry on subcutaneous tumor xenografts of these cells in immunodeficient mice." (PMID 28262839, 2017). "Further computational analysis based on immunohistochemistry data confirmed that EPHB6 expression is reduced in at least 60% of the TNBC tumours, when compared to its mean expression level in the matching normal tissue." (PMID 27418135, 2016). "Ephrin type-B receptor 6 (EPHB6) influences cell adhesion and migration, the expression of which is usually down regulated during tumor progression." (PMID 27463019, 2016). "In contrast, TNBC tumours expressing EPHB6 are likely to have higher levels of the active, phosphorylated form of DRP1, a fragmented mitochondrial network and therefore be more sensitive to the DR5-initiated apoptotic signal." (PMID 27788485, 2016). "Our observations are of potential practical importance, as they imply that DR5-activating therapeutic approaches should be applied in a more personalized manner to primarily treat EPHB6-expressing tumours." (PMID 27788485, 2016). "This of course would require a further evaluation of EPHB6 function in freshly obtained tumour samples." (PMID 27418135, 2016). "For example, relapse samples gained mutations in transmembrance receptor tyrosine kinase genes EPHB2 and EPHB6, whose family member EPHA7 encodes a known soluble tumor suppressor for FL." (PMID 25123191, 2014). "However, transfection of SK-N-DZ neuroblastoma cells with an AS-MIF expression vector reduced MIF expression, leading to a decrease in pro-tumor genes such as N-Myc, TrkB, Ras, and IL-8, while tumor-suppressing genes like EPHB6 and BLU were elevated." (PMID 41159021, 2025). "Notably, ULBP1 is an immune system-activating receptor on natural killer cells and T cells, and EPHB6 has been shown to suppress tumor invasion and metastasis." (PMID 40837413, 2025). "The results showed that EphB6 can be used as a new prognostic marker for this tumor." (PMID 40421081, 2025). "analyzing the immunoexpression of EphB6 in 54 samples of this tumor." (PMID 40421081, 2025). "In several malignancies, an inverse correlation between EphB6 expression and tumor aggressiveness was observed thereby suggesting that EphB6 may suppress invasive and metastatic phenotypes." (PMID 38341842, 2024). "Interestingly, genetic analyses showed that when EphB6 overexpression is accompanied by mutations in the APC gene, the tumor gains significant advantages in cell proliferation, invasion, and metastasis." (PMID 38651144, 2024).
tumor (continued). "However, step 6 activity of recognition of tumor cells by T cells was significantly downregulated in the EPHB6-low expression group (p<0.001), probably owing to the high level of inhibitory immune checkpoints stimulating immune escape." (PMID 37637034, 2023). "By using microarray technology it was reported that in MIF-reduced NB cells there was a downregulation of certain genes associated with tumor development including IL-8 and C-met along with upregulation of the tumor-suppressor genes EPHB6, visinin-like protein 1 (VSNL-1), and BLU." (PMID 32155795, 2020). "Interestingly, consistent with EPHB6 ability to support tumoursphere expansion and tumour initiation, its silencing significantly suppressed ALDH1-positive HCI-010 population, which is expected to maintain TIC activity." (PMID 29700392, 2018). "Remarkably, tumours formed by EPHB6-expressing TICs proved to be much more sensitive to treatment with doxorubicin, which could be in part due the ability of EPHB6 to convert TICs into faster proliferating, less resistant cells." (PMID 29700392, 2018). "As in cell lines-based models, EPHB6 silencing was maintained in PDX tumours." (PMID 29700392, 2018). "In addition, a similar effect of EPHB6 silencing on tumour growth was observed with TNBC cells, BT-20." (PMID 29700392, 2018). "This apparent discrepancy may be due to the different antibodies used in these two studies for the assessment of EPHB6 levels in tumor samples." (PMID 28262839, 2017). "In addition, tumor volume was significantly increased in mice injected with IMCE-Wt-EphB6 cells compared with the control." (PMID 27145271, 2016). "Our model may also potentially be applicable to multiple other tumor types, where EPHB6 expression is reduced according to previously published observations and according to our findings reported here." (PMID 27418135, 2016). "For instance a recent study proposed that EPHB6 could decide the fate of the tumor by interacting with other receptors such as EPHB2 and EPHA2." (PMID 26870995, 2016). "The results of our past studies and those presented herein emphasize that whether TNBC tumours express EPHB6 should be a serious consideration with respect to choosing the most efficient therapeutic treatment options." (PMID 27788485, 2016). "EphB4 and EphB6 were also significantly elevated in tumor epithelium relative to ‘normal’ samples." (PMID 21935409, 2011). "Interestingly, numerous reports have also described the role of EphB6 as a tumor suppressor." (PMID 40065768, 2025). "Importantly, this implies that EPHB6 may be used as a new biomarker for selecting TNBC tumours sensitive to DR5 activation and that DR5 agonists could produce better results if used selectively to treat EPHB6-positive tumours." (PMID 27788485, 2016). "Notably, the cells with lower expression of WT-EphB6-mNG, termed WT-EphB6-mNGsorted-low, exhibited a similar amplitude of invasiveness to those of other EphB6 mutants, indicating that the EphB6 expression level may be important for curbing tumor cell invasion." (PMID 38627519, 2024). "However, for patients with advanced or metastatic BLCA, EPHB6-directed therapy could potentially serve as a stimulator to immune checkpoint inhibitors (ICIs), reprogramming a cold immune tumor microenvironment into a hot one, which merited further study and investigation." (PMID 37637034, 2023). "EPHB6 was described as an epithelial–mesenchymal transition suppressor in TNBC cells and increased tumor sensitivity against drug therapy in TNBC xenograft models and cell lines." (PMID 31412533, 2019). "Collectively, these data strongly support the notion that EPHB6 enhances expansion of TIC populations and promotes tumour development." (PMID 29700392, 2018). "Consistent with our initial results, silencing of EPHB6 expression in HCC70 decreased tumour growth and tumour initiation, and reduced TIC frequency." (PMID 29700392, 2018).
tumor (continued). "We previously demonstrated that the low expression of favorable NB genes (EFNB2, EFNB3, EPHB6, NTRK1, CD44 and MIZ-1), as well as that of the tumor growth suppressive gene, EPHA2, in NB cell lines was due to epigenetic silencing." (PMID 24190252, 2014). "Thus, to investigate the impact of the EphB6:ephrinB1 co-clusters on MDA-MB-231 cell invasiveness, we performed three-dimensional tumor spheroid invasion assays, monitoring the area of invasion on a focal plane." (PMID 38627519, 2024). "BLCA is an immunogenic tumor type, and an in-depth investigation of Eph receptor/EFN ligand family genes in BLCA identified that inactive kinase EPHB6 may be a potential therapeutic target." (PMID 37637034, 2023). "In tumor-to-stroma signaling, primary and metastatic lesions are characterized by EFNA2 interacting with EPHA1, EFNB3 interacting with EPHB2, and EFNB3 interacting with EPHB6, among several others." (PMID 36676129, 2023). "Unlike other EPH receptors, EPHB6 lacks tyrosine kinase activity and shows tumor-suppressive effects." (PMID 31160603, 2019). "Therefore, we examined EPHB6 effect on proliferation of TNBC cells producing tumourspheres, as tumourspheres better represent tumour behaviour than cells cultured in monolayers and are predominantly formed by TICs." (PMID 29700392, 2018). "Moreover, doxorubicin also efficiently suppressed tumours initiated by HCC70 cells, while EPHB6 silencing enhanced their resistance." (PMID 29700392, 2018). "This analysis was done across 25 different tumor types and specifically searched for a negative correlation between expression of EPHB6 and a SL gene." (PMID 27418135, 2016). "Although no drugs have been directly targeted at EPHB6, related pathway-regulating drugs could potentially affect its expression and/or activity and then regulate tumor cell biology." (PMID 37637034, 2023). "Moreover, EPHB6 does not regulate the growth of tumor cells in vitro or in vivo either in a xenograft model or in mouse knockout models after genetic/carcinogen tumor initiation." (PMID 28262839, 2017). "Thus, interventions that support its activity, including the application of stabilizing anti-EphB6 antibodies, with the simultaneous administration of DR5 agonists may improve tumour eradication." (PMID 27788485, 2016). "This suggests that EPHB6 does not have a blanket effect on TICs, but most likely promotes specific subsets of these cells, and agrees very well with TIC heterogeneity, which results from the evolution of TICs in developing tumours." (PMID 29700392, 2018).
kidney diseases (1 paper, 2018). "mRNAs coexpressed with lncRNAs were involved in many kidney diseases, e.g., Ephb6 was associated with the reabsorption ability of the kidney." (PMID 30200873, 2018).
neurological disorders (1 paper, 2022). "Ephb6 and Tnik were also downregulated in Kdm6a KO cells derived from reciprocal crosses consistent with immunopathological phenotypes and neurological disorders seen in the syndrome." (PMID 35871105, 2022).
EPHB6 also shares sentences with these, for which no sentence is quoted: hepatocellular carcinoma (4 papers); T-cell acute lymphoblastic leukemia (3); adenocarcinoma (2); gastric cancer (2); hypogonadism (2); anaplastic astrocytoma (1); Anxiety (1); autistic spectrum disorder (1); benign moles (1); bladder cancer (1); brain disorder (1); cervical cancer (1); cognitive decline (1); colitis (1); colorectal (1); combined immunodeficiency (1); dementia (1); diffuse astrocytoma (1); familial Alzheimer disease (1); familial colorectal cancer (1); glaucoma (1); Intellectual disability (1); medullary sponge kidney disease (1); medulloblastoma (1); mesonephric adenocarcinoma (1); metastatic melanoma (1); metastatic tumors (1); neurodevelopmental disorder (1); Obesity (1); osteosarcoma (1).
A further 10 diseases each share a sentence with EPHB6 in 1 paper.